RNU6-287P (RNA, U6 small nuclear 287, pseudogene)
Gene: Small nuclear RNA gene on chromosome 17 (42,891,338 to 42,891,435, reverse strand). Ensembl gene ENSG00000252039.
Homologues: Orthologues: chimpanzee U6 (98% identical), macaque U6 (91% identical), dog U6 (80% identical), rabbit U6 (80% identical), rat LOC120095355 (66% identical). Paralogues in human: RNU6-183P (85% identical), RNU6-1209P (84% identical), RNU6-1007P (83% identical), RNU6-35P (83% identical), RNU6-739P (83% identical), RNU6-1175P (82% identical), RNU6-11P (82% identical), RNU6-204P (82% identical), RNU6-20P (82% identical), RNU6-23P (82% identical), RNU6-37P (82% identical), RNU6-398P (82% identical), and 1284 more.